S100A9 (S100 calcium binding protein A9)
Diseases named in the same sentence as S100A9 in open-access papers (continued):
Sharing a sentence is not in itself a finding about the gene and the disease.
contact dermatitis (6 papers, 2012 to 2025). An inflammatory skin condition caused by direct contact between the skin and either an irritating substance or an allergen. "The S100A8/S100A9 tetramer modulates the immune response in skin granuloma and irritant contact dermatitis models by regulating the basal migration of monocytes through specific interactions with CD69." (PMID 40270593, 2025). "To evaluate the feasibility of monitoring S100A9 expression by optical imaging, we employed irritant contact dermatitis (ICD) as an inflammatory model, exclusively driven by innate immunity, independent of the adaptive immune system." (PMID 25098555, 2014). "It is demonstrated that extracellular S100A8/S100A9 tetramers significantly dampen monocyte dynamics as adhesion, migration, and traction force generation in vitro and immigration of monocytes in a cutaneous granuloma model and inflammatory activity in a model of irritant contact dermatitis in vivo." (PMID 36310133, 2022). "In contact dermatitis, as a model of local inflammation, we could demonstrate that the expression of S100A9 is a very sensitive marker for inflammatory processes and reflects disease activity independently of the underlying pathomechanism, for example, in toxic or in allergen-induced inflammation." (PMID 25098555, 2014). "Previous analysis of the skin response to P. ovis infestation demonstrated an increase in the expression of S100A9 and the putative conserved roles of S100A8 and S100A9 in contact dermatitis and sheep scab have been discussed previously." (PMID 22880105, 2012).
dermatitis (6 papers, 2016 to 2024). An inflammatory process affecting the skin. "After topical 2,4-dinitrochlorobenzene (DNCB) treatment, Stat3 cKO mice developed worsened AD-like skin inflammation with increased Ki67+ cells, decreased filaggrin and loricrin expression, and downregulated S100A9 and LL37." (PMID 38053996, 2023). "However, in this study, we observed robust Th17 responses as well as expression of IL-17A signature genes (i.e., S100a8, S100a9, CAMP, and LCN2) in the skin of Nfkbiz−/− mice with spontaneous dermatitis." (PMID 28740238, 2017). "Furthermore, IL-17A target genes (i.e., S100a9, S100a8, CAMP, and LCN2) were remarkably upregulated in the skin of Nfkbiz−/− mice with dermatitis." (PMID 28740238, 2017).
dry eye (6 papers, 2011 to 2021). "Protein S100-A9 is a proinflammatory protein with increased levels in tears from dry eye patients and positively correlated to disease intensity." (PMID 33372592, 2020). "In a study using the isobaric tagging for relative and absolute quantification (iTRAQ) technology, we found the S100A8 and S100A9 proteins were among a panel of 6 upregulated proteins found in the tear of dry eye patients." (PMID 26605353, 2014). "The average ratio of S100A8 and S100A9 in dry eye versus control subjects was 1.82 (SD 1.41) and 1.92 (SD 1.48) respectively." (PMID 26605353, 2014).
endotoxemia (6 papers, 2012 to 2023). "We used S100A8/A9 blockade with the small-molecule inhibitor ABR-238901 and S100A9−/− mice for therapeutic and mechanistic studies on endotoxemia-induced cardiac dysfunction in mice." (PMID 37773186, 2023). "IL-22 (F-652) protects against LPS-induced cytokines storm in the LPS-induced endotoxemia model by inducing the expression of APPs from the liver, like S100A9, and thereby inducing F4/80+Ly6GhiLy6Chi M2-like suppressor cells differentiation." (PMID 36123595, 2022). "Our study suggests that IL-22 has a protective role against endotoxemia by inducing the development of immunosuppressive cells through S100A9." (PMID 36123595, 2022). "In summary, our findings suggest that F-652 (IL-22) protects mice against LPS-induced endotoxemia by promoting M2-like macrophage polarization, and this process may depend on S100A9." (PMID 36123595, 2022). "Therefore, IL-22 induced more suppressive Ly6Chi cells in the LPS-induced endotoxemia model, probably by inducing S100A9 production in the liver." (PMID 36123595, 2022). "In contrast to data derived from a murine endotoxemia model using the same mouse strain, but in line with our in vitro data, S100A9 deficiency did not have a marked effect on cytokine and chemokine levels during S. Typhimurium infection." (PMID 25860480, 2015).
esophageal squamous cell carcinoma (6 papers, 2015 to 2024). Esophageal squamous cell carcinoma (ESCC) is a type of esophageal carcinoma (EC) that can affect any part of the esophagus, but is usually located in the upper or middle third. "For example, almost all members of the S100 family were highly expressed in ESCA, consistent with previous studies demonstrating high expression of S100A7, S100A8, and S100A9 in esophageal squamous cell carcinoma (ESCC), which predicted cancer cell migration and worse overall survival." (PMID 38684596, 2024). "However, decreased expression of S100A8 and S100A9 in Chinese esophageal squamous cell carcinoma were also reported." (PMID 34934042, 2021). "S100A8/S100A9 expression could be detected in 74.4% of lung SCCs, 100% of esophageal SCCs, 100% of cervical SCCs, 96% of oral SCCs, and 95% of skin SCCs stained positive for both S100A8/S100A9." (PMID 31208368, 2019).
glomerulonephritis (6 papers, 2013 to 2025). A renal disorder characterized by damage in the glomeruli. "Serum S100A8 and S100A9 levels reflect disease activity in ANCA-associated vasculitis, glomerulonephritis and systemic lupus erythematosus." (PMID 29795379, 2018). "In the context of active glomerulonephritis, such as rapidly progressive glomerulonephritis, infiltrating macrophages have a dominant M1 proinflammatory phenotype, and M1 polarization can be triggered by lipopolysaccharide and S100A9 to produce a range of proinflammatory molecules." (PMID 40191205, 2025). "Another study proved that conditional ablation of the S100A8 gene in myeloid cells or general knockout of the S100A9 gene in mice could ameliorate glomerulonephritis and obstructive nephropathy phenotypes due to inflammatory response inhibition." (PMID 38110934, 2023).
ischemia (6 papers, 2020 to 2025). A hypoperfusion of the BLOOD through an organ or tissue caused by a PATHOLOGIC CONSTRICTION or obstruction of its BLOOD VESSELS, or an absence of BLOOD CIRCULATION. "This study confirms that S100A9 is a key regulator of I/R progression and may participate in ischemia-reperfusion injury by upregulating RAGE /NFKB-NLRP3 activation." (PMID 40069854, 2025).
liver fibrosis (6 papers, 2018 to 2023). "Taken together, these results imply TRPM8 deficiency may attenuate liver fibrosis by downregulating the expression of the pro-inflammatory factor S100A9 while promoting the expression of HNF4α." (PMID 35525986, 2022). "In conclusion, our results suggest that TRPM8 inhibition may alleviate the liver fibrosis caused by inflammation and cholangiopathies through S100A9-HNF4α signaling." (PMID 35525986, 2022). "The inhibition of TRPM8 has the potential to mitigate liver fibrosis by downregulating the expression of the pro-inflammatory factor S100A9 and promoting the expression of HNF4α." (PMID 37569884, 2023). "IHC and enzyme-linked immunosorbent assay (ELISA) results showed that S100A8 and S100A9 were both significantly elevated in liver fibrosis patients compared to HCs." (PMID 36429008, 2022). "As two members of DAMPs, S100A8 and S100A9, can serve as triggering factors and amplifiers of inflammation, and we have previously found that S100A9 increases in liver fibrosis." (PMID 36429008, 2022). "And the gradual increase of S100A9 levels in regressive mice upon insult offers further support for the major contribution of hepatic fibrosis in S100A9 inhibition." (PMID 33462187, 2021). "It is worth noting that our previous study demonstrated an elevated S100A9 in liver fibrosis." (PMID 36429008, 2022). "Notably, S100A8 increased more dramatically than S100A9 during the progression of liver fibrosis from fibrosis F0 to F4." (PMID 36429008, 2022). "Similarly, elevated levels of S100A8 and S100A9 were verified in clinical samples and CCl4-induced mouse model studies, and their levels were strongly related to the severity of liver fibrosis." (PMID 36429008, 2022). "Therefore, hepatic fibrosis holds a pivotal place in suppressing necroptosis- and S100A9-dependent necroinflammation." (PMID 33462187, 2021). "Specifically, S100A8 increased more dramatically than S100A9 during the progression of liver fibrosis, implying an important role of S100A8 in the pathogenesis of liver fibrosis." (PMID 36429008, 2022). "Given this, we hypothesized that S100A8 and/or S100A9 may regulate NLRP3 inflammasome-dependent pyroptosis to establish a proinflammatory microenvironment, thereby potentiating the progression of liver fibrosis." (PMID 36429008, 2022).
lymph node metastasis (6 papers, 2012 to 2026). "Gastric patients with high counts of S100A9 positive cells also associate with less lymph node metastasis." (PMID 26431492, 2015). "S100A8 and S100A9 were elevated in more than 50% of CRC tissues and their expression in tumor cells was associated with differentiation, Dukes stage and lymph node metastasis." (PMID 23637971, 2013). "We found that S100A8 and S100A9 were elevated in CRC, and their expression in tumor cells was associated with the differentiation, Dukes stage and lymph node metastasis." (PMID 23637971, 2013). "High S100A9-positive cell count was negatively correlated with lymph node metastasis (P = 0.009) and tumor invasion (P = 0.011)." (PMID 22838504, 2012). "We found that both MDSCs and S100A9 are correlated to Dukes staging and lymph node metastasis, and activation of the RAGE-mediated p38 MAPK and TLR4-mediated NF-κB signaling pathways are involved in S100A9-induced trafficking and activation of MDSCs, respectively." (PMID 31620141, 2019). "While the differentiating power of S100A9, MDSCs or their combination is weak for CRC diagnosis, the combination detection could a marker for predicting CRC stages and lymph node metastasis." (PMID 31620141, 2019). "In the present study, we confirmed the elevation of S100A8 and S100A9 in CRC and found that their elevation in tumor cells was not only associated with histological differentiation but also with Dukes stage and lymph node metastasis in CRC." (PMID 23637971, 2013).
mastitis (6 papers, 2014 to 2025). Inflammation of breast tissue during lactation or postpartum due to an obstructed duct or infection. "S100 calcium-binding protein A9 encoding gene S100A9 has previously been shown to be actively involved in inflammatory processes and upregulated in bovine mastitis." (PMID 35804592, 2022). "Among these, seven genes (CXCR1, HCK, IL1RN, MMP9, S100A9, GRO1, and SOCS3) were identified as the hub genes and these can be explored as potential candidate genes for mastitis susceptibility and resistance." (PMID 35723402, 2022). "Muribaculaceae, a beneficial commensal bacteria demonstrated by several studies, had a lower relative abundance in cows with subclinical mastitis and was negatively correlated with the expression S100A9 in this study." (PMID 35804592, 2022). "Protein S100-A9, Protein S100-A8, Chitinase-3-like protein 1, Haptoglobin, Integrin beta-2, and Chloride intracellular channel protein 1 were more abundant in milk-derived EVs for clinical mastitis." (PMID 36611779, 2023). "Among these, seven genes—CXCR1, HCK, IL1RN, MMP9, S100A9, GRO1, and SOCS3—were identified as the hub genes (highly connected genes) for mastitis susceptibility and resistance, and were subjected to protein-protein interaction (PPI) network and gene regulatory network construction." (PMID 35723402, 2022). "In the present study, proteins S100A12, S100A8 and S100A9, were up-regulated by 11.17, 5.1 and 5.1 folds in the mastitis-infected mammary glands, which is consistent with the previous report, further demonstrating their roles in the immune response to pathogen infection." (PMID 25273983, 2014). "This suggests that in the context of mastitis, upregulation of S100A8, S100A9, and S100A12 enhances the production of pro-inflammatory cytokines and Chemokines to maintain host homeostasis." (PMID 41156687, 2025). "The most important overexpressed genes in cows with mastitis were GRO1, CXCR1, SOCS3, S100A9, MMP9, HCK, and IL1RN, which were hub genes (highly connected genes) involved in mastitis in this study." (PMID 35723402, 2022).
Myocardial fibrosis (6 papers, 2020 to 2025). "More recently, a study demonstrated that infarct size was significantly decreased, cardiac contractile function was improved, CM death was markedly reduced, and myocardial fibrosis was lessened in mice with global S100A9 deficiency following I/R, which suggests a detrimental role of S100A9." (PMID 33282877, 2020). "To explore the effect of inhibiting S100a9 on myocardial fibrotic remodeling, we continuously administered intraperitoneal injections of the inhibitor for one week and assessed myocardial fibrosis levels in the mice." (PMID 38323308, 2024). "Furthermore, the histological analysis of myocardial tissues using Masson-trichrome and Sirius red staining demonstrates an aggravation of myocardial fibrosis after cardiac-specific overexpression of S100A9." (PMID 40384874, 2025). "On the day 1 and 7 post-reperfusion, the high expression of Tgf-β in the hearts of WT mice could be effectively alleviated in S100a9-/- mice, which was accompanied by a reduction in the area of myocardial fibrosis." (PMID 38323308, 2024). "Masson staining suggested that the S100a9 inhibitor effectively alleviated myocardial fibrosis." (PMID 38323308, 2024). "In addition, mice treated with S100A9 neutralizing antibody (nAb) can observe a significant reduction in infarcted areas, increased cardiac function, and reduced myocardial fibrosis after I/R." (PMID 39175627, 2024). "Furthermore, a significantly reduced infarct region, increased cardiac function, and decreased myocardial fibrosis were observed post-I/R in mice treated with a S100A9 neutralizing antibody (nAb)." (PMID 33282877, 2020).
pancreatic ductal adenocarcinoma (6 papers, 2018 to 2023). An infiltrating adenocarcinoma that arises from the epithelial cells of the pancreas. "Pancreatic ductal adenocarcinoma (PDAC) is characterised by a highly reactive microenvironment, harbouring a variety of cell types, including S100A8/S100A9-expressing monocytes." (PMID 30558665, 2018). "In pancreatic diseases, previous studies have indicated that pancreatic ductal adenocarcinoma (PDAC) patients with elevated levels of S100A9 in the ductal fluid have a notably worse prognosis 20 and the plasma level of S100A9 is also significantly increased in AP mice and patients 21,22." (PMID 33754072, 2021).
peritonitis (6 papers, 2012 to 2024). Inflammation of the peritoneum (tissue that lines the abdominal wall and covers most of the organs in the abdomen). "High amounts of S100A8/A9 were released in the peritoneal lavage fluid and plasma of peritonitis affected mice, and this lead to liver and lung damage, and high cytokine production, because in S100A9 KO mice, the organ damage was reduced and the cytokine production was diminished." (PMID 29180999, 2017). "In a collagenase-induced OA model, S100A8 and S100A9 expression remained elevated long after inflammatory cytokine levels had subsided, while in a BCP crystal-induced peritonitis model, both peritoneal and serum concentrations of S100A8 and S100A9 were increased." (PMID 28173838, 2017).
psoriatic arthritis (6 papers, 2014 to 2025). Joint inflammation associated with psoriasis. "S100A8/ S100A9 alarmin is strongly expressed in the synovial sublining layers of psoriatic arthritis." (PMID 36700196, 2022). "S100 calcium-binding proteins like S100A8 and S100A9 play a role in regulating inflammation in psoriatic arthritis." (PMID 34108969, 2021). "Similarly, in Pa patients, S100A8 and S100A9 are expressed in skin lesions and present in elevated levels in the serum, and these proteins are also considered potential markers for psoriatic arthritis." (PMID 39877611, 2025).